LGALS7 (galectin 7)
Description:
Could be involved in cell-cell and/or cell-matrix interactions necessary for normal growth control. Pro-apoptotic protein that functions intracellularly upstream of JNK activation and cytochrome c release.
Synonyms: PIG1; GAL7; TP53I1; LGALS7A
Target class: Other cytosolic protein
Gene: Protein-coding gene on chromosome 19 (38,770,968 to 38,773,517, reverse strand). Ensembl gene ENSG00000205076.
Subcellular location: Cytoplasm; Nucleus; Secreted
Pathways (Reactome):
Developmental Biology: Differentiation of Keratinocytes in Interfollicular Epidermis in Mammalian Skin
Gene Ontology:
Molecular function: protein binding; carbohydrate binding
Biological process: heterophilic cell-cell adhesion
Cellular component: extracellular exosome; extracellular region; cytoplasm; nucleus
Homologues: Orthologues: mouse Lgals7 (78% identical), rat Lgals7 (64% identical), Drosophila melanogaster galectin (34% identical), zebrafish lgals3b (33% identical), Caenorhabditis elegans lec-3 (32% identical), Caenorhabditis elegans lec-1 (31% identical), Caenorhabditis elegans lec-6 (31% identical), Caenorhabditis elegans C27C7.5 (29% identical), zebrafish si:dkey-95h12.2 (29% identical), Caenorhabditis elegans F40H6.5 (28% identical), Caenorhabditis elegans lec-12 (28% identical), Caenorhabditis elegans lec-8 (27% identical), and 12 more. Paralogues in human: LGALS7B (100% identical), LGALS4 (39% identical), LGALS9 (38% identical), LGALS9B (38% identical), LGALS9C (38% identical), LGALS8 (35% identical), LGALS1 (32% identical), LGALS3 (32% identical), LGALS16 (29% identical), CLC (28% identical), LGALS13 (28% identical), LGALS14 (28% identical), and 4 more.
Diseases named in the same sentence as LGALS7 in open-access papers:
LGALS7 is named in the same sentence as 75 diseases in open-access papers, as found by Europe PMC text mining. Sharing a sentence is not in itself a finding about the gene and the disease. The quoted sentences say what the papers report.
breast carcinoma (20 papers, 2013 to 2025). "A higher level of galectin 7 was associated with tumor suppression in neuroblastoma and colon cancer but enhanced the progression of breast cancer and lymphoma." (PMID 38503797, 2024). "They demonstrated that breast cancer cells expressing mutated galectin-7 were equally or even more resistant to drug-induced apoptosis, compared to cells expressing wt galectin-7." (PMID 34827718, 2021). "Both galectin-3 and galectin-7 were associated with mammary tumour progression with galectin-7 being correlated to pejorative diagnosis when accumulated while reduced galectin-3 was of better prognosis." (PMID 29257082, 2017). "As with other aggressive subtypes of breast cancer, these tumors are associated with abnormally high expression of galectin-7 (gal-7), which confers metastatic breast tumor cells with increased invasive behavior." (PMID 27902734, 2016). "For example, data obtained from a study using an experimental breast carcinoma model and a study evaluating clinical specimens collected from patients with thyroid cancer revealed that high galectin-7 expression levels were associated with cancer progression and aggressiveness." (PMID 34198494, 2021). "In breast cancer, the earliest report on galectin-7 being associated to oncogenesis is from a chemically induced mammary tumour in rat which was found to overexpress galectin-7 contrastingly to chemically induced colon carcinomas which express a reduced level of galectin-7." (PMID 29257082, 2017). "Furthermore, overexpression of galectin-7 was associated to metastatic potential of various tumour tissues, notably in breast cancer." (PMID 29257082, 2017). "However, galectin-7 has been associated with cancer progression in chemically induced models of rat mammary carcinoma and human hypopharyngeal squamous cell carcinoma." (PMID 23658821, 2013). "However, its role in promoting tumor malignancy was also described in several reports, and galectin-7 expression was linked to increased metastatic phenotype in breast cancers and migration of corneal epithelial cells." (PMID 23985992, 2013). "For instance, galectin-7 overexpression has been shown to significantly increase the ability of breast cancer cells to metastasize to lungs and bones." (PMID 38927753, 2024). "In breast cancer cells, overexpression of galectin-7 led to a significant increase in lung metastases and osteolytic lesions." (PMID 39465762, 2024). "In breast cancer cells and in lymphomas, the overexpression of galectin-7 led to increased metastasis." (PMID 39465762, 2024). "In cancer diseases, the expression of galectin-7 varies depending on the type of cancer: elevated levels have been observed in esophageal squamous cell carcinomas and breast cancer cells, likely due to the ability of galectin-7 to protect cells from apoptosis." (PMID 39337670, 2024). "High expression levels of galectin-7 were found in aggressive subtypes of breast cancer, frequently with a basal-like phenotype and estrogen receptor-negative tumors." (PMID 36873388, 2023).
breast carcinoma (continued). "We and others have since shown that galectin-7 can induce MMP-9 in breast cancer, ovarian cancer, head and neck cancer, cervical and oral squamous cell carcinomas and, more recently, gastric cancer cells." (PMID 34198494, 2021). "Bibens-Laulan and St-Pierre uncovered how galectin-7 traffics between both intracellular and extracellular compartments in ovarian and breast cancer cells." (PMID 34827718, 2021). "Grosset and co-workers confirmed the expression of galectin-7 in the cytosolic and nuclear compartments of breast cancer cells and the ability of galectin-7 to translocate to mitochondria." (PMID 34827718, 2021). "An important mediator of galectin-7 gene activation in breast cancer cells, CCAAT/enhancer-binding protein beta or C/EBPβ, was suggested to contribute by the same group in 2014." (PMID 34827718, 2021). "For example, galectin-7 has been shown to promote metastasis in breast cancer, but it is tumor suppressive in gastric cancer." (PMID 34638303, 2021). "Galectin-7 is also believed to increase the invasive behavior of breast cancer cells; the ability to metastasize to the lungs and bones increased in mouse models." (PMID 34827718, 2021). "The expression of galectin-7 was observed in the cytoplasm as well as in the nucleus of breast cancer cells." (PMID 34827718, 2021). "It is believed that breast cancer cells overexpressing galectin-7 are related to the ability of galectin-7 to protect against apoptosis." (PMID 34827718, 2021). "Galectin-7 (Gal-7), like Gal-1 and Gal-3, seems to have tumor-promoting effects: in a Gal-7 deficient mouse model, a delayed development of HER2+ breast cancer was observed." (PMID 32290551, 2020). "Recently, using a mouse model for ErbB2 mammary tumours, galectin-7 expression was reported to accelerate tumour progression and the formation of tumour nodules in ErbB2-positive tumours." (PMID 29257082, 2017). "Taken together, our findings suggest that C/EBPβ is an important mediator of galectin-7 gene activation in breast cancer cells and highlight the different transcriptional mechanisms controlling galectin-7 in cancer cells." (PMID 24789216, 2014). "Similar results were obtained when we increased galectin-7 expression, consistent with our previous findings that high levels of galectin-7 increase metastasis of breast cancer cells to the bone and the lung." (PMID 24789216, 2014). "We have since confirmed the specific expression pattern of galectin-7 in breast cancer tissues using tissue microarrays (TMAs) constructed from samples obtained from normal individuals and in patients with breast carcinomas." (PMID 24789216, 2014). "Taken together, these results indicate that increased expression of C/EBPβ-2 is sufficient to induce galectin-7 in breast cancer cell lines and possibly other types of cells." (PMID 24789216, 2014). "We and others have since shown that galectin-7 is also expressed in breast cancer tissues in humans." (PMID 24789216, 2014). "This is especially true for breast cancer where galectin-7 expression is readily expressed in a high proportion in basal-like breast cancer tissues, conferring cancer cells with increased resistance to cell death and metastatic properties." (PMID 24789216, 2014). "Using preclinical mouse models, we have further shown that high levels of galectin-7 expression in breast cancer cells increase their ability to metastasize to lungs and bones." (PMID 24789216, 2014).
breast carcinoma (continued). "Taken together, these results identify a novel regulatory pathway that regulates galectin-7 expression in human breast cancer cells." (PMID 24789216, 2014). "Close examination of a number of public databases supports the view that C/EBP is a positive regulator of galectin-7 in breast cancer cells." (PMID 24789216, 2014). "Our results showed that ectopic expression of C/EBPβ-2 in human breast cancer cells was sufficient to induce expression of galectin-7 at both the mRNA and protein levels." (PMID 24789216, 2014). "While a clear picture of the function of galectin-7 in breast cancer is emerging, very little is known about the molecular mechanisms regulating galectin-7 expression in human breast cancer cells." (PMID 24789216, 2014). "More specifically, we found that increased expression of C/EBPβ-2 is sufficient to upregulate galectin-7 expression at both mRNA and protein levels in breast cancer cells." (PMID 24789216, 2014). "To address this paradox, we have examined the molecular mechanisms regulating galectin-7 in breast cancer cells." (PMID 23967302, 2013). "High expression of galectin-7 in breast cancer cells induced their ability to metastasize to lungs and bones, and many breast carcinoma samples contain more than 70% galectin-7– positive cells." (PMID 23985992, 2013). "In the present work, we have examined this apparent contradiction by investigating the molecular mechanisms controlling galectin-7 expression in human breast cancer cells." (PMID 23967302, 2013). "We and others have previously found that galectin-7 was expressed in mammary tissues of aggressive subtypes of breast cancer cells." (PMID 23967302, 2013). "Over-expression of galectin-7 modulated the aggressive behavior of lymphoma cells through expression of the metastasis-related gene MMP-9 and the expression of galectin-7 was increased in rat mammary carcinomas induced by carcinogen." (PMID 23985992, 2013). "In fact, in breast cancer, overexpression of galectin-7 alone is sufficient to promote metastasis to the bone and lung." (PMID 23658821, 2013). "In colon cancer, for example, galectin-7 has an anti-tumorigenic function, in contrast to its pro-tumorigenic function reported in lymphoma, breast cancer, squamous cell carcinoma of the tongue and esophagus, and thyroid malignancies." (PMID 23658821, 2013). "Using tissue microarrays constructed from samples obtained from normal breast tissues and breast carcinomas, we previously reported that galectin-7 was expressed at abnormally high levels in tissues collected from patients with a poor prognosis." (PMID 23967302, 2013). "Studies using experimental mouse models have further shown high expression of galectin-7 was sufficient to increase the metastatic behavior of poorly metastatic breast cancer cells, rendering them more resistant to apoptosis." (PMID 23967302, 2013). "In addition, galectin-7 proved to accelerate tumor progression in one of the most aggressive forms of breast cancer (HER-2 positive) as was published in a subsequent study, using genetically engineered galectin-7–deficient mice." (PMID 34827718, 2021). "In fact, we found that both can bind to the LGALS7 promoter in breast cancer cells." (PMID 34198494, 2021).
breast carcinoma (continued). "Later on, galectin-7 was scored among the differentially expressed gene on human breast cancer." (PMID 29257082, 2017). "Future investigations will thus be needed to determine whether direct suppression of galectin-7 expression or via specific targeting C/EBPβ are valuable alternatives to inhibit breast cancer progression." (PMID 24789216, 2014). "There is an increasing number of reports, however, showing that galectin-7 is overly expressed in cancer cells, most notably in as esophageal, lung and buccal squamous cell carcinomas, thyroid carcinomas, bladder cancer, lymphoma, and breast cancer." (PMID 24789216, 2014). "In the present work, we have examined whether C/EBPβ regulates expression of galectin-7 in breast cancer cells." (PMID 24789216, 2014). "We first set out to determine if the C/EBPβ-2 isoform could induce galectin-7 gene expression in human breast cancer cell lines." (PMID 24789216, 2014). "Because high levels of NF-κB have been associated with resistance to apoptosis, and galectin-7 induces resistance to apoptosis in breast cancer cells, our results suggest that galectin-7 may contribute to NF-κB-mediated resistance to apoptosis." (PMID 23967302, 2013). "Moreover, galectin-7 overexpression in murine lymphoma and breast cancer cells has been shown to increase their ability to metastasize." (PMID 23658821, 2013). "Interestingly, we found that this mutant induced galectin-7 expression in MCF-7 breast cancer cell line while binding to the endogenous galectin-7 promoter." (PMID 23967302, 2013). "However, whether the resistance of breast cancer cells to apoptosis is dependent on the intracellular localization of galectin-7 remains unknown." (PMID 34827718, 2021). "The β-galactoside binding protein galectin-7 (gal-7) is constitutively expressed at abnormally high levels in the outside milieu and intracellular compartments of many types of epithelial cancer cells, most notably in aggressive forms of ovarian and breast cancer." (PMID 29117220, 2017). "This provided the first indication that galectin-7 expression could be modulated in breast cancer." (PMID 24789216, 2014). "However, in some cases, such as breast cancer and lymphoma, its high expression level correlates with aggressive subtypes of cancer, suggesting that galectin-7 may have a dual role in cancer progression." (PMID 23658821, 2013). "Galectin-7 also enhances spontaneous metastasis in both human epidermal growth factor receptor 2 (HER2) overexpressed and basal-like lineages of breast cancer." (PMID 36873388, 2023). "Consistent with this, a previous study of breast carcinoma has demonstrated that Galectin-7, absent in low-grade but upregulated in high-grade, is associated with increased metastasis to the lungs and bones." (PMID 40718829, 2025). "For example, another mutant, R273H, induces galectin-7 in breast cancer cells but not in ovarian cancer cells." (PMID 34198494, 2021). "Galectin-7 (gal-7) was recently shown to be specifically expressed in basal-like but not in luminal subtypes of human breast cancer." (PMID 25367122, 2014).
breast carcinoma (continued). "Combining the results suggested that galectin-7 might be an independent negative prognostic factor in breast cancer and a therapeutic target, especially in HER2-positive breast cancer." (PMID 34827718, 2021). "Galectin-7 was only elevated in stage I (p = 0.0206) and not in later stages of breast cancer." (PMID 34638303, 2021). "Using the ONCOMINE public cancer microarray database, we also found that C/EBPβ was expressed at significantly higher levels in oestrogen receptor (ER)-negative and triple-negative (TN) breast cancer tissues, a pattern identical to that of galectin-7 in human breast cancer tissues." (PMID 24789216, 2014). "This abnormally high expression level of galectin-7 is not restricted to breast cancer cells." (PMID 23967302, 2013). "Their data revealed that while galectin-7 transcripts were expressed at low levels in normal breast tissues and mammary epithelial cell lines, they were highly expressed in estrogen receptor (ER)-negative breast cancer and in cell lines with a basal-like phenotype." (PMID 23967302, 2013).